L1CAM (L1 cell adhesion molecule)
Diseases named in the same sentence as L1CAM in open-access papers (continued):
Sharing a sentence is not in itself a finding about the gene and the disease.
cancer (continued). "Overexpression of L1CAM in normal and cancer cells increases motility, enhances growth rate and promotes cell transformation and tumorigenicity." (PMID 24422715, 2013). "Because of its involvement in a wide variety of human cancers, L1CAM has been considered as a target molecule for cancer therapeutics." (PMID 22888955, 2012). "L1 cell adhesion molecule (CD171) is expressed in many malignant tumors and its expression correlates with unfavourable outcome." (PMID 21600041, 2011). "From a neural recognition molecule in brain development to a potential marker in cancer progression, this de novo function of L1CAM has been uncovered in several cancer types." (PMID 20840789, 2010). "Our data provides new evidence for the function of L1CAM and its soluble form in promoting cancer cell adhesion to ECM and cell migration." (PMID 20840789, 2010). "The distinction of L1CAM presence in cancerous vs. normal tissues has suggested it to be a new target for cancer treatment." (PMID 20840789, 2010). "Neural recognition molecule L1CAM, which is a key protein involved in early nervous system development, is known to be abnormally expressed and shed in several types of cancers where it participates in metastasis and progression." (PMID 20840789, 2010). "In many human epithelial carcinomas L1CAM is overexpressed and thereby augments cell motility, invasion and metastasis formation." (PMID 20799950, 2010). "The upregulation of multiple lineage plasticity genes, including basal (Trp63, Krt5 and Krt14), metastasis (Snai2, Tgfb1 and L1cam), and stemness (Sox2, Mecom and Sox6) markers was induced by LKB1 loss, further supporting the enhanced cancer cell state plasticity by LKB1 loss." (PMID 39743630, 2025). "However, since L1CAM is upregulated in various cancer types, its role in the broader differential diagnosis of renal cell neoplasms needs further exploration." (PMID 40805143, 2025). "L1CAM has been also recognized as a regulator of cancer stemness in other malignances." (PMID 40429728, 2025). "Furthermore, L1CAM’s involvement in various cellular interactions, especially in the context of cancer, raises concerns about its precision in distinguishing NDEVs." (PMID 39742488, 2025). "L1CAM (CD171) is suggested to play a critical role in cancer." (PMID 41328908, 2025). "In line with this notion, another study using all three—L1CAM, IMP3, and progesterone receptor (PR)—improved the diagnostic accuracy in preoperative endometrial samples compared to morphological assessment alone in detecting high-grade carcinomas." (PMID 40870967, 2025). "The dynamic nature of L1CAM adhesion interactions may be particularly beneficial for cancer cells seeking cooperative vasculature when invading tissues, mediating and participating in vascular co-option of BMS cancer cells." (PMID 38590656, 2024). "L1CAM appears to act as an oncogene in many kinds of cancer." (PMID 39201435, 2024). "Moreover, we used L1CAM as a marker of neuron-derived EVs, which has been controversial in recent years because it is also upregulated in cancer cells." (PMID 39409091, 2024). "Therefore, in theory, inhibition of L1CAM can not only suppress VC by preventing cancer cells motility and adhesion but also increase the efficacy of chemotherapy or immunotherapy inducing vascular normalization." (PMID 38737903, 2024). "Additionally, the downregulation of L1CAM in LUAD metastasis contrasts with its known role in promoting invasion in other cancers, revealing a more complex and context-dependent role of L1CAM in cancer biology." (PMID 39697539, 2024). "L1CAM has been found in various types of human cancers, which indicates a bad prognosis." (PMID 36925653, 2023). "Moreover plasmin induces the destroying of L1CAM (L1 cell adhesion molecule) expressed by cancer cells, preventing their ability to coopt brain capillaries." (PMID 38293652, 2023).
cancer (continued). "Additionally, elevated L1CAM expression has been reported to confer cancer stem cell properties in a variety of tumors and has been associated with poorer outcomes in many cancer types." (PMID 37928520, 2023). "L1CAM is a transmembrane protein that is involved in increasing invasiveness, motility and metastatic potential, and has been found to be a poor prognostic factor in several cancers." (PMID 37081760, 2023). "Furthermore, disseminated cancer cells employ cell adhesion molecule L1 (L1CAM) to spread on capillaries and activate the mechanotransduction effectors Yes-associated protein (YAP) and myocardin-related transcription factor (MRTF)." (PMID 37190188, 2023). "Additionally, SCs can foster PNI by secreting L1 cell adhesion molecule (L1CAM), which not only attracts cancer cells through the activation of MAPK signaling, but also upregulates metalloproteinase by STAT3 activation." (PMID 35455973, 2022). "On the contrary, human monoclonal antibody (MAb) approaches might be investigated in NSMP/L1CAM-positive patients, as already reported in various types of cancer." (PMID 36358847, 2022). "The control of L1CAM expression in cancer has therefore drawn widespread research attention." (PMID 35473609, 2022). "In addition, in supratentorial (ST) EPN, NOTCH1 expression was associated with cancer stem cell (CSC) markers, VEGFA and L1CAM, and the ST_EPN_RELA subtype showed the activation of selected key members of the Notch signaling pathway (NOTCH1, JAG1, JAG2, HES4)." (PMID 36293188, 2022). "Besides, a multitude of studies showed that L1CAM is overexpressed in a variety of human cancers (for review, see Ref." (PMID 34228897, 2022). "Consistent with previous findings, L1CAM plays a key role in EC cancer cell migration and adhesion." (PMID 36212450, 2022). "Emerging evidence indicates that the synchronous expression of the L1CAM and platelet count in cancer and peripheral blood may lead to a plethora of interactions between cancer and platelet, which will add to the functional significance of this cross-talk." (PMID 36387224, 2022). "The L1 cell adhesion molecule (L1CAM) is a type-1 transmembrane molecule that is over-expressed in various types of human cancers, including HGSC and may thus play an important role in neoplastic processes." (PMID 36509990, 2022). "HIF-1a and TGF-β1 are EMT regulators that also regulate L1CAM expression in cancer cells." (PMID 34078883, 2021). "PLAT encodes a tissue type plasminogen activator, and it has been shown that its activation target, plasmin, can inhibit brain metastasis by releasing FasL from astrocytes to promote cancer cell death, as well as inactivating the adhesion molecule L1CAM important for cancer spreading." (PMID 34948172, 2021). "These different L1CAM expression may contribute to the contrasting roles of L1CAM in cancer cells and normal ECs." (PMID 34078883, 2021). "Alternatively, the metastatic properties of secreted L1CAM may be responsible for its effects on cancer progression." (PMID 33897875, 2021). "L1CAM positivity was mainly, but not exclusively, found in intermediate- and high-risk cancers (13.2 vs 25.8% in low and intermediate, respectively)." (PMID 34540651, 2021). "Interestingly, we also observed upregulations of genes involved in axonal guidance—L1 cell adhesion molecule (L1CAM), neuropilin-1, semaphorins, and ephrins, indicating potential interactions of cancer cells and neuronal components of the stroma." (PMID 35008571, 2021). "It seems that cancer cells including MDA-MB-231 cells exhibit aberrant expression of L1CAM." (PMID 34078883, 2021). "Surprisingly, L1CAM expression has been highlighted in several types of cancer." (PMID 33167483, 2020). "We speculate that this difference may be due to different expression patterns and different histopathological types of L1CAM in different types of cancer." (PMID 32742486, 2020).
cancer (continued). "Besides the role of L1CAM in cancer stemness, it is worth mentioning that a few studies have implicated the molecule also in normal stem cells." (PMID 32429448, 2020). "Indeed, several studies found a correlation between soluble L1CAM levels in liquid biopsies from cancer patients and different clinical parameters." (PMID 32429448, 2020). "Using the ELDA (Extreme Limiting Dilution Analysis) software we estimated that the cancer cell-initiating frequency of double-positive (1/1756) was eight times higher in comparison to the one of L1CAM+/CD133− (1/14749) and eight times higher than SKOV3ip wild-type cells (1/13963)." (PMID 31952346, 2020). "Due to the expression and function of L1CAM in cancer stem cells for some tumors, the possibility of imaging this cell subpopulation might be of help not only for prognostic purposes but also to monitor the evolution of the disease." (PMID 32429448, 2020). "Recent evidence has demonstrated L1CAM as an oncogenic driver in various malignancies, and the clinical burden and prognostic biomarker potential of L1CAM expression evaluated by immunohistochemistry has been shown in several cancers, including GC." (PMID 31754264, 2019). "Moreover, as L1CAM is a potential target for novel cancer therapies, understanding specific domain functions is important for targeted therapy." (PMID 31455004, 2019). "Thus, the question how domain-specific forms of L1CAM contribute to cancer progression can only be partially answered, challenging L1CAM’s clinical applicability." (PMID 31455004, 2019). "Finally, due to the strict selection criteria we chose to apply, many L1CAM-mediated pathways that have been identified in non-cancer cells were left out of this systematic review, even though those will likely have direct relevance for cancer progression." (PMID 31455004, 2019). "In conclusion, L1CAM has an important role in cancer progression and its main functions can be separated into biological processes and signaling initiated directly by the L1CAM molecule, and the activation of processes that rely on autocrine- and paracrine signaling." (PMID 31455004, 2019). "Taken together with the data presented here, these findings raise the hypothesis that NOVA2 regulates AS of L1CAM in cancer vessels." (PMID 30829570, 2019). "Both L1CAM-FL and its cleavage products exert biological functions, but the specific contributions of differentially processed L1CAM forms in the plasma membrane, the intracellular or extracellular environment to cancer progression are incompletely understood." (PMID 31455004, 2019). "Recently, SerpinB2 in BCCs was shown to promote cancer cell survival and metastatic outgrowth by converting astrocytic FasL into a paracrine death signal for cancer cells, and by inactivating L1 cell adhesion molecule (L1CAM) to spread metastatic cells along brain capillaries." (PMID 28427146, 2017). "Subsequently, we addressed whether L1CAM contributed to the fibroblast Mint3-mediated cancer cell proliferation." (PMID 28504692, 2017). "In addition, L1CAM prevents the maturation of cancer vasculature and its inhibition promotes vessel normalization, a process that is thought to improve the therapeutic response of tumors to cytotoxic drugs." (PMID 28134764, 2017). "Thus, fibroblast Mint3-mediated cancer cell proliferation can indeed be attributed to L1CAM in fibroblasts." (PMID 28504692, 2017). "In conclusion, the present comprehensive meta-analysis of 37 studies with 8552 patients suggests that high L1CAM expression might be a prognostic factor for poor outcome in patients with various cancer types." (PMID 27833079, 2016). "L1CAM mRNA expression in type I cancers was 2.9-fold lower than in type II tumors (p=0.01)." (PMID 27174921, 2016). "Overall, the results obtained for all of the endpoints evaluated showed that L1CAM might serve as an unexceptionable biomarker to predict the unfavourable outcomes for cancer patients." (PMID 27833079, 2016).
cancer (continued). "For most of the investigated cancer types, L1CAM demonstrated a significant prognostic value." (PMID 27833079, 2016). "L1-CAM exhibits various properties that provide rationale for targeting it in cancer therapies." (PMID 26761817, 2016). "Interestingly the L1CAM expression was 1.5-fold higher in those women with platinum refractory cancers compared to those being sensitive (0.32 vs 0.22)." (PMID 27174921, 2016). "L1CAM, has been extensively investigated in the last 15 years in relation to its capacity in enhancing cell motility and thereby promoting invasiveness in a variety of human cancers." (PMID 27233077, 2016). "In the univariate survival analysis the 11% L1CAM positive cancers exhibited an unfavourable DFS (median value 1.21 (Q1-Q3 0.50-2.13) years VS 8.63 (Q1-Q3 2.48-14.62) years; p=0.005) and OS (median value 3.51 (Q1-Q3 1.11-8.43) years VS 12.12 (Q1-Q3 5.83-16.06) years p=0.020);." (PMID 27233077, 2016). "However, it has been shown that these small islands of L1CAM positive cells in cancers are of clinical relevance." (PMID 27174921, 2016). "Over the past decade, the knowledge of L1CAM in the cancer field has developed rapidly." (PMID 27833079, 2016). "Cancer patients with excessive L1CAM expression had a poor prognosis." (PMID 27833079, 2016). "We showed an upregulation of L1CAM in the 5-FU-resistant cells, which is in line with previous findings that support the hypothesis that L1CAM is upregulated by cancer cells as a part of the EMT process." (PMID 25860483, 2015). "Therefore, there is a considerable cancer type-dependent effect of the L1CAM on the EMT-like phenotype." (PMID 25294816, 2014). "As the L1CAM recently emerged as a key driver in cancer cell growth and metastasis, it might serve as a potential RNAi target in advanced cancers." (PMID 25294816, 2014). "However, little is known about molecular mechanisms that suppress the expression of L1CAM in cancers." (PMID 24497324, 2014). "Thus, the present finding showing that AR can regulate L1CAM in a direct fashion adds a novel element to the complex regulation of L1CAM in cancer." (PMID 25510351, 2014). "It will be interesting to study whether the stratification of these cancers based on L1CAM expression will show other commonalities presently unknown." (PMID 25510351, 2014). "It was identified that the downregulation of L1CAM inhibited the intrinsic activation of ERK1/2 in Capan-2 cells, indicating that L1CAM may be involved in cancer cell progression via the p38/ERK1/2 signaling pathway." (PMID 24660028, 2014). "Interestingly, recent reports have shown that in cancer cell lines the L1CAM expression is augmented by treatment with DNA-demethylation agents that affect the methylation status of the L1CAM promoter." (PMID 24497324, 2014). "Furthermore, higher numbers of CD3+ T cells as well as low expression of FoxP3 and L1CAM in carcinoma cells tended to be correlated with prolonged patient survival." (PMID 24797069, 2014). "Several studies have shown that L1CAM positive carcinomas have a bad prognosis." (PMID 24497324, 2014). "L1CAM was localized mainly in the cytoplasm of primary cancer cells." (PMID 24422715, 2013). "The L1CAM-induced cell motility was shown to involve a direct interaction of the shed L1CAM ectodomain, or the full-length L1CAM, with integrins, implying that L1CAM may play a role in cancer promotion and metastasis by also mediating cell-ECM interactions." (PMID 22888955, 2012). "Given that L1CAM is rarely present other than in the nervous system, immune effector cells, and kidney under normal circumstances, its constitutive expression and shedding in tumors makes it an ideal marker for cancer detection and treatment." (PMID 20840789, 2010).
cancer (continued). "Effects of various growth factors in cancer tissues also may contribute to the abnormal presence of L1CAM." (PMID 20840789, 2010). "Surface proteins, such as N-CAM, Ng-CAM, L1CAM and neogenin, which predominantly exert effects in nervous system development, have been demonstrated also to facilitate tumor cell progression in certain types of cancer." (PMID 20840789, 2010). "Also, the percentage of patients with high level L1CAM expression was shown to increase with the advance of cancer progression." (PMID 20840789, 2010). "Indeed, overexpression of L1CAM has been reported in carcinomas such as ovarian and endometrial, colon, pancreas, kidney, cholangiocarcinoma, gastric cancer but also melanoma." (PMID 20799950, 2010). "In any case, how exactly L1CAM controls its cellular effects—especially in the case of cancer cells, where it seems to offer them increased motility and invasiveness, as well as an epithelial-to-mesenchymal phenotype—remains unclear and warrants further research." (PMID 40870967, 2025). "To uncover L1CAM-regulated signaling pathways, we employed quantitative proteomics and phosphoproteomics, which have become an indispensable tool for a deeper understanding of cancer biology and identification of clinically relevant pathways suitable for therapeutic intervention." (PMID 40429728, 2025). "Combining inhibition of mTORC1 or DNAPKC signaling with radio-chemotherapy has shown promising results in cancer therapy, suggesting that targeting L1CAM, which influences DNA repair and mTORC1 signaling, could be a valuable approach for further therapeutic exploration." (PMID 40429728, 2025). "However, L1CAM protein can be aberrantly expressed in various cancer types." (PMID 41328908, 2025). "Survival maps from the GEPIA2 database showed that among the 33 analyzed cancer types, increased expressions of ADAMTS1, L1CAM, and EGFR were only significantly associated with poor survival in HNSCC, implying the critical and specific role of the ADAMTS1-L1CAM-EGFR axis in HNSCC progression." (PMID 38263290, 2024). "Considering that the development and progression of BCLM may be due to adhesion and extravasation of cancer cells to normal sinusoidal vessels, we hypothesized that the expression patterns of L1CAM, YAP/TAZ, and β1-integrin might reflect the gross pattern of BCLM represented with radiologic studies." (PMID 35628976, 2022). "Finally, we set out to identify L1CAM target genes and investigated the expression of ezrin, galectin‐3, and FGFb, which had already been described as L1CAM targets or binding partners in other cancer entities." (PMID 34228897, 2022). "Additionally, to address whether the effects of L1CAM on cancer cells differed from those on normal ECs, we compared L1CAM expression in MDA-MB-231 cells and HUVECs." (PMID 34078883, 2021). "Hence, it is not surprising that, due to its causal role in CSC biology, L1CAM has been also implicated in these processes in cancer, even though these studies were not always conducted on CSC subpopulations." (PMID 32429448, 2020). "In fact, L1CAM undergoes endocytosis, which is enhanced by antibody binding, supporting the hypothesis that antibody-drug conjugates would represent suitable tools against L1CAM-expressing cancer cells." (PMID 32429448, 2020). "Therefore, if the new form of L1CAM can be detected in the blood, it could be used to help cancer diagnosis, and to indicate which patients would benefit from treatments that restrict the growth of blood vessels in tumors." (PMID 30829570, 2019). "Thus, co-stimulation via other membrane protein(s) might be necessary for a directional proliferation signalling from fibroblasts to cancer cells by L1CAM-integrin α5β1 interaction." (PMID 28504692, 2017). "There are three hypotheses how L1CAM is upregulated in cancer." (PMID 27028855, 2016). "In addition, multiple clinical pathology studies have indicated that L1CAM may promote cancer cell invasion and metastasis." (PMID 24660028, 2014).